RBM3 (RNA binding motif protein 3)
Diseases named in the same sentence as RBM3 in open-access papers (continued):
Sharing a sentence is not in itself a finding about the gene and the disease.
perinatal asphyxia (1 paper, 2011). A disorder caused by a lack of blood flow or gas exchange to or from the fetus in the period immediately before, during, or after the birth process. "Recent reports indicate that induction of RBM3 is essential for the protective effects of hypothermia in models of perinatal asphyxia and muscle wasting." (PMID 22145045, 2011).
prostate intraepithelial neoplasia (1 paper, 2011). A neoplastic proliferation of the epithelial cells that line the acini and the ducts of the prostate gland. "While rarely expressed in benign prostate gland epithelium, RBM3 was found to be up-regulated in prostate intraepithelial neoplasia and present in various fractions and intensities in invasive prostate cancer." (PMID 21955582, 2011).
subarachnoid hemorrhage (1 paper, 2025). A serious neurological disorder characterized by intracranial hemorrhage into the subarachnoid space. "Importantly, stabilizing rG4 through increasing intracellular potassium with an FDA-approved potassium channel blocker, mimics the hypothermic effect on alternative splicing, thereby increasing RBM3 expression, leading to RBM3-dependent neuroprotection in a mouse model of subarachnoid hemorrhage." (PMID 40968270, 2025). "Using RBM3 exon 3a as a model, we show that increasing intracellular potassium ion through the broad voltage-gated potassium channel blocker 4-aminopyridine (4-AP) stabilizes rG4s, leading to RBM3-dependent neuroprotection in a subarachnoid hemorrhage mouse model." (PMID 40968270, 2025).
testicular germ cell tumor (1 paper, 2015). A germ cell tumor arising from the testis. "In testicular germ cell tumor (TGCT), RBM3 was expressed in various intensities and fractions, mainly in the nucleus but also in the cytoplasm, with a particularly strong expression in seminomatous components." (PMID 25811459, 2015).
tuberculosis (1 paper, 2022). A chronic, recurrent infection caused by the bacterium Mycobacterium tuberculosis. "Furthermore, we validated the accuracy of some differentially expressed genes in an independent cohort using quantitative PCR, and obtained three novel genes (RBM3, CSRNP1, SRSF5) with the ability to discriminate active tuberculosis from LTBI and HC." (PMID 36059536, 2022).
tumor (44 papers, 2010 to 2026). "RBM3-associated germline variants contribute to GC susceptibility, and RBM3 downregulation promotes aggressive tumor behavior." (PMID 41994650, 2026). "A similar study revealed that patients with a high expression of RBM3 were associated not only with a low tumor grade but also with a low risk of lymphovascular invasion (lymph node invasion)." (PMID 36831493, 2023). "Further insight into the mechanistic basis underlying the role of RBM3 in tumor progression and chemotherapy sensitivity is however needed." (PMID 29464064, 2018). "The association of high RBM3 expression with BRAF wild type tumours is in accordance with earlier reports." (PMID 28800641, 2017). "High RBM3 expression was strongly and significantly associated with lower T-stage and low-grade tumours (p = 0.001 for both)." (PMID 28293425, 2017). "High nuclear RBM3 expression was statistically significant associated with BRAF wild type tumours, and RBM3 expression was significantly higher in patients who underwent secondary surgery and received irinotecan based treatment." (PMID 28800641, 2017). "Nowadays, accumulating immunohistochemically studies have suggested RBM3 function as a proto-oncogene that is associated with tumor progression and metastasis in various cancers." (PMID 28118608, 2017). "Membranous expression of podocalyxin-like protein 1 (PODXL) and low expression of the RNA-binding motif 3 (RBM3) has previously been shown to be associated with an aggressive tumour phenotype and poor prognosis in several forms of cancer, including UBC." (PMID 28293425, 2017). "Univariable Cox regression analysis confirmed the significant association between low RBM3 expression and a shorter 5-year OS in the entire cohort (HR 3.19; 95% CI 2.02–5.02) and in T1 tumours (HR 2.64; 95% CI 1.11–6.27)." (PMID 28293425, 2017). "A large variety of immunohistochemical studies, including many tumor types, have shown consistently that loss of RBM3 expression is associated with clinically more aggressive tumors and an independent factor of poor prognosis." (PMID 27147467, 2016). "In the present study, we also examined the associations of RBM3 expression with the proliferation marker Ki67 in primary tumours and metastases." (PMID 24963396, 2014). "The precise functional mechanisms behind loss of RBM3 and a more aggressive tumour behaviour remain to be elucidated." (PMID 23565664, 2013). "Next, we examined the association between RBM3 expression, disease progression within 24 months and 5-year OS in patients with Ta and T1 tumours." (PMID 23565664, 2013). "This revealed a significant positive association between RBM3 expression and a younger age at diagnosis (p=0.013), lower T-stage (p<0.001) and high grade tumours (p=0.004)." (PMID 23565664, 2013). "Reduced nuclear RBM3 expression was significantly associated with more advanced tumour (T) stage (p <0.001) and high grade tumours (p=0.004)." (PMID 23565664, 2013). "Although this pro-survival function might appear contradictory in the oncologic context, where enhanced cell survival could promote tumor progression, elevated RBM3 expression has been consistently associated with improved clinical outcomes." (PMID 40506997, 2025). "Its involvement in immune evasion mechanisms, potentially influencing tumor-associated macrophages and regulatory T cells, suggest that RBM3 may influence immunotherapy outcomes." (PMID 40506997, 2025). "A potential explanation is that RBM3 may contribute to maintaining a more differentiated tumor phenotype, which is typically associated with less aggressive behavior and favorable prognosis." (PMID 40506997, 2025). "A high expression of RBM3 has been linked to better prognosis in numerous studies on clinical tumor specimens, suggestively through inhibition of tumor growth and dissemination, where influence of DNA damage checkpoint protein levels is one possible mechanism." (PMID 32491279, 2020).
tumor (continued). "Conversely, RBM3 is also associated with inhibition of tumor growth and dissemination." (PMID 28118608, 2017). "The high expression of RBM3, which is associated with improved patient survival and cisplatin sensitivity, may help to predict tumor behavior and guide optimized personalized therapy in individuals." (PMID 28118608, 2017). "Apart from indicating that loss of RBM3 is an early event in adenocarcinoma of the upper gastrointestinal tract, these findings also support that analysis of RBM3 in the primary tumour is sufficient for prognostic and, potentially, treatment predictive purposes." (PMID 24963396, 2014). "Low RBM3 expression was significantly associated with a reduced OS in the full cohort (p = 0.003) and in cases with radically resected (R0) primary tumours (p = 0.002)." (PMID 24963396, 2014). "Low RBM3 expression was significantly associated with a shorter OS in cases with radically resected (R0) tumours (HR 2.19, 95% CI 1.33-3.61, p = 0.002) and RFS in curatively treated patients with R0 resection/distant metastasis-free disease (HR = 3.21, 95% CI 1.64-6.30, p = 0.001)." (PMID 24963396, 2014). "Speculatively, these findings could indicate that loss of RBM3 expression results in a tumour phenotype more prone to metastatic spread than local aggressiveness." (PMID 23565664, 2013). "It is therefore plausible to assume that tumours with high RBM3 expression may well recur, while loss of RBM3 expression will generate a disease more likely to muscle invasion and distant spread." (PMID 23565664, 2013). "Apart from these studies, we are not aware of any other publications related to the prognostic or treatment predictive impact of the tumour-specific expression of RBM3 in human cancer, and the biological processes underlying these observations have not yet been unraveled." (PMID 21777469, 2011). "On the other hand, once a tumour has been established, an attenuated capability of DNA-damage response caused by RBM3 over expression might hinder the pressure for selection of more malignant clones." (PMID 21955582, 2011). "Thus, MIR4435-2HG sponges miR-383-5p to cause RBM3 overexpression and promote tumor progression." (PMID 36313570, 2022). "The fact that the impact on progression-free survival in patients with Ta and T1 tumours was not as significant may be due to the lower number of events, and therefore, the association between RBM3 expression and tumour progression merits further validation in other cohorts." (PMID 23565664, 2013). "It acted as a tumor suppressor by binding to RBM3 and promoting degradation of uXBP1 mRNA, a key ER stress molecule." (PMID 40745648, 2025). "Future studies integrating molecular stratification and larger subtype-specific cohorts are warranted to clarify RBM3’s prognostic role within specific tumor subtypes." (PMID 40506997, 2025). "The identification of DEPs comparing ACA, ACC, and PMAH with NHAsamples revealed the downregulation of RNA-binding motif protein 3(RBM3) in all neoplasms analyzed when compared to NHA." (PMID 41269005, 2025). "Functional experiments are needed to clarify RBM3’s role in chemoresistance, metastasis, and tumor microenvironment interactions." (PMID 40506997, 2025). "We found that RBM3, a cold shock protein that plays important roles in various cellular processes, including neural repair, apoptosis, and damage, ER stress, and tumor development, is a potential interacting protein of circFAM13B." (PMID 40745648, 2025). "As a stress-response protein, RBM3 also has RNA-binding properties which play a crucial role in determining the fate of cancer cells in the tumor microenvironment." (PMID 36750551, 2023). "Through mechanistic studies, we found that RBM3 significantly reduced stem-like properties of tumor cells by inhibiting alternative splicing of CD44v8-10." (PMID 37190171, 2023).
tumor (continued). "Patient 3 had a heterogenous expression of RBM3, with low expression in the lymph node metastases and a higher expression in the primary tumour and peritoneal metastases." (PMID 35169225, 2022). "For example, it has been shown that MIR4435-2HG expression was markedly upregulated in HNSCC tissues and contributed to tumor progression via regulation of the miR-383-5p/RNA-binding motif protein 3 (RBM3) axis." (PMID 35328568, 2022). "Patients with high-tumour specific RBM3 expression treated with NAC had a significantly reduced risk of recurrence and a prolonged CSS and OS compared to NAC-untreated patients." (PMID 35109796, 2022). "In contrast to the present study, treatment status has not been previously accounted for, thus providing a possible explanation for the paradoxical relationship between upregulation of the proto-oncogene RBM3 and an improved outcome in advanced tumours." (PMID 35109796, 2022). "RBM3 protein expression was significantly higher in TURB compared to cystectomy specimens but showed consistency between primary tumours and lymph node metastases." (PMID 35109796, 2022). "Investigation of RBM3 protein expression on TMAs instead of whole tumor sections is also a limitation." (PMID 32491279, 2020). "RBM3 overexpression enhanced the development of multicellular tumor spheroids in NIH3T3 mouse fibroblasts." (PMID 31440515, 2019). "It has been reported that RBM3 alters miRNA levels which in turn will modify global protein expression and thus tumor progression." (PMID 31440515, 2019). "In ESCC, decreased RBM3 expression was associated with advanced UICC stage, high tumor stage, and positive lymph node status (P = 0.0213, P = 0.0061, and P = 0.0192)." (PMID 30419865, 2018). "Earlier studies on RBM3 expression in other malignancies have often indicated a biological and clinical significance of RBM3 expression, but results varied substantially between tumor entities." (PMID 30419865, 2018). "Only one immunohistochemical study has so far analysed RBM3 expression in upper gastrointestinal adenocarcinomas using a tissue microarray containing of 175 tumor specimens." (PMID 30419865, 2018). "The authors also found a significantly higher RBM3 expression in normal squamous epithelium as compared to primary tumours." (PMID 30419865, 2018). "High cytoplasmic RBM3 expression was significantly associated with age <75 years, BRAF wild type tumour, secondary surgery and irinotecan based treatment." (PMID 28800641, 2017). "In muscle-invasive (T2–T4) tumours, there was a borderline significant trend towards a reduced 5-year OS for tumours with low RBM3 expression (p = 0.061)." (PMID 28293425, 2017). "Kaplan-Meier analysis of OS revealed that patients with tumours displaying high nuclear or cytoplasmic RBM3 expression who received oxaliplatin based treatment as first-line chemotherapy had significantly longer survival compared to all other strata." (PMID 28800641, 2017). "This study examined the prognostic impact of PODXL and RBM3 expression in tumours from incident cases of UBC in a large, population-based cohort." (PMID 28293425, 2017). "Specifically, knockdown of RBM3 in tumor cells increases caspase-mediated apoptosis coupled with nuclear cyclin B1, and phosphorylated Cdc25c, Chk1, and Chk2 kinases, implying that under conditions of RBM3 downregulation, cells undergo mitotic catastrophe." (PMID 27147467, 2016). "In conclusion, whereas both CIRP and RBM3 show common characteristics of proto-oncogenes at the cellular level, their roles in the clinical tumor setting are diverse, with CIRP as a marker of poor prognosis and RBM3 as a marker of good prognosis." (PMID 27147467, 2016). "There was a significant difference in mean score of RBM3 expression between tumours from patients in CS I and CS II-IV, Mk+ in all three categories." (PMID 25811459, 2015). "In other types of tumours, RBM3 expression has been found to be upregulated in preinvasive and cancerous tissues." (PMID 25811459, 2015).
tumor (continued). "The FFS was significantly inferior for patients with low tumour-specific RBM3 expression [59.3% versus 79.0% (p=0." (PMID 25811459, 2015). "Immunohistochemical RBM3 expression was analysed in tissue microarrays with tumours from 206 patients." (PMID 25811459, 2015). "Here, we examined the clinicopathological correlates and prognostic significance of RBM3 expression in tumours from a consecutive cohort of upper gastrointestinal adenocarcinoma." (PMID 24963396, 2014). "RBM3 expression was similar in primary tumours and lymph node metastases, but significantly higher in primary tumours and metastases arising in a background of intestinal metaplasia compared with cases without intestinal metaplasia (p < 0.001)." (PMID 24963396, 2014). "In patients with Ta and T1 tumours expressing reduced RBM3 levels, Kaplan-Meier analysis revealed a significantly shorter PFS (p=0.048) and 5-year OS (p=0.006)." (PMID 23565664, 2013). "If RBM3 modulates tumor behavior through specific signaling pathways, the pharmacologic targeting of its activity may represent a novel therapeutic strategy in OC." (PMID 40506997, 2025). "RBM3 may also interact with the tumor microenvironment, particularly through the modulation of immune cell infiltration and inflammatory responses." (PMID 40506997, 2025). "RBM3 also modulates several biological processes relevant to cancer, including apoptosis, DNA repair, and cell proliferation, thereby influencing tumor behavior and its response to treatment." (PMID 40506997, 2025). "In addition, the function of RBM3 in tumors and the mechanistic pathways it depends on can be elucidated and extended to more tumor treatments." (PMID 36831493, 2023). "RBM3 protein expression level in tumour cells was assessed via immunohistochemistry in paired transurethral resection of the bladder (TURB) specimens, cystectomy specimens and lymph node metastases from a consecutive cohort of 145 patients, 65 of whom were treated with NAC." (PMID 35109796, 2022). "The knockdown of RBM3 also led to the growth arrest of tumor xenografts." (PMID 35328637, 2022). "Tumour-specific RBM3 protein expression could be evaluated in TURB specimens from 141/145 (97.2%) cases, in cystectomy specimens from 89/135 (65.9%) cases and in lymph node metastases from 25/27 (92.6%) cases." (PMID 35109796, 2022). "Further analysis of NAC-treated patients according to RBM3 expression showed that the fraction of pathological downstaging of the primary tumour was higher in patients with high RBM3 expression compared to low RBM3 expression; however, this was not statistically significant (p = 0.156)." (PMID 35109796, 2022). "Moreover, an in vitro study showed that miR-383-5p overexpression abrogated the tumor-promoting effects of MIR4435-2HG by repressing RBM3 expression." (PMID 36313570, 2022). "Of note, IL-33 has been reported to promote a tumor hypoxic microenvironment, with generation of reactive oxygen species, that could lend toward an indirect induction of RBM3 through local hypoxia." (PMID 35908044, 2022). "The RBM3 gene is a proto-oncogene that is involved in tumor progression and metastasis." (PMID 33670352, 2021). "Moreover, this type of ncRNA expression was dynamically regulated by RNA-binding protein 3 (RBM3) that had an important impact on SCD-circRNA 2 expression in tumor cells." (PMID 33020462, 2020). "RBM3 has been suggested to have potential proto-oncogene and tumor suppressive roles in cancer." (PMID 30419865, 2018). "In addition, the effects of siRNA-mediated knockdown of RBM3 on chemotherapy response and tumor cell migration and invasion were investigated in vitro." (PMID 29464064, 2018). "So far, pro-oncogenic as well as tumor suppressive functions of RBM3 have been suggested." (PMID 30419865, 2018).